RNU6-1158P (RNA, U6 small nuclear 1158, pseudogene)
Gene: Small nuclear RNA gene on chromosome 17 (56,871,170 to 56,871,276, forward strand). Ensembl gene ENSG00000212469.
Homologues: Orthologues: chimpanzee U6 (100% identical), macaque U6 (96% identical), dog U6 (86% identical). Paralogues in human: RNU6-574P (93% identical), RNU6-38P (93% identical), RNU6-1011P (92% identical), RNU6-166P (92% identical), RNU6-476P (92% identical), RNU6-17P (91% identical), RNU6-18P (91% identical), RNU6-21P (91% identical), RNU6-25P (91% identical), RNU6-338P (91% identical), RNU6-33P (91% identical), RNU6-468P (91% identical), and 1287 more.